AREG (amphiregulin)
Diseases named in the same sentence as AREG in open-access papers (continued):
Sharing a sentence is not in itself a finding about the gene and the disease.
gastric cancer (16 papers, 2013 to 2025). A primary or metastatic malignant neoplasm involving the stomach. "IGF1R gene expression was associated with poor outcomes after curative resection of stage II/III gastric cancer, whereas AREG gene expression was associated with good outcomes." (PMID 26884344, 2017). "30reported the adverse result about AREG expression in gastric cancer through mRNA level that AREG gene expression was associated with good outcomes." (PMID 28256068, 2017). "In conclusion, the current study provided compelling evidence that high IGF1R and low AREG expression were associated with poor prognosis after curative resection of stage II/III gastric cancer." (PMID 26884344, 2017). "Furthermore, we found an overexpression of MMP-9, that promotes tumor invasion and is associated with poor prognosis in gastric cancer, ANXA1 and ANXA4, overexpressed in gastric cancer and associated with proliferation, AREG, that promotes malignant progression in several types of cancer." (PMID 34012923, 2021). "Amphiregulin is an EGFR ligand that is frequently overexpressed in human gastric cancer and promotes epithelial proliferation and survival, making its loss an interesting paradoxical model for studying growth factor dependencies." (PMID 40673273, 2025). "Mechanistically, it therefore seems likely that the HDACi-mediated upregulation of the AREG-EGFR axis in gastric carcinoma cells represents a combination of direct and indirect effects." (PMID 39864337, 2025). "As there are now several therapies available to target EGFR signaling during cancer, more work is needed to clarify the role(s) of amphiregulin in our model and in gastric cancer." (PMID 37674528, 2023). "Our lab have been studied two papers about the expression of two genes in gastric cancer, respectively 17 (Bing W,2016,oncotarget, accepted) and found Trop2 and AREG was all overexpression in GC tissues." (PMID 28256068, 2017). "To investigate the effects of exogenous ligands on the trastuzumab sensitivity of gastric cancer cells, we performed a concomitant treatment of gastric cancer cell lines with AREG, EGF or HB-EGF and trastuzumab." (PMID 27933395, 2017). "CXCL2 upregulation is clinically relevant as this neutrophil chemoattractant is elevated in human gastric cancer and correlates with increased angiogenesis and tumor progression, while amphiregulin promotes epithelial proliferation and is frequently overexpressed in human gastric adenocarcinomas." (PMID 40673273, 2025). "The unwanted entinostat-mediated stimulation of the amphiregulin-EGFR axis in gastric cancer described for the first time in this study may thus be an important factor in an adaptive response of the tumor cells." (PMID 39864337, 2025). "AREG may serve as a combined marker of prognosis in gastric cancer, and the combined detection of Trop2 and AREG could help predict the prognosis of gastric cancer patients." (PMID 37604948, 2023). "Only a few studies have investigated the expression of AREG in gastric cancer." (PMID 27933395, 2017). "However, results published recently by our group identified AREG secretion in combination with other factors as a positive predictor of cetuximab response in gastric cancer cell lines." (PMID 27933395, 2017). "In addition, increases in EGF-related peptides HB-EGF and amphiregulin are evident in patients with H. pylori infection and/or gastric cancer." (PMID 25437333, 2013). "A pro-tumorigenic role of ILC2s is the production of amphiregulin (AREG), a strong inhibitor of tumor responses that contributes to the recruitment and activation of regulatory T cells (Tregs), also associated with a poor prognosis in breast, ovarian and gastric cancers." (PMID 34680190, 2021). "Besides HB-EGF, other ErbB ligands (transforming growth factor-α (TGF-α) and amphiregulin (AREG)) have a prognostic impact on gastric cancer and might make up potential targets in cancer therapy." (PMID 32340207, 2020).
gastric cancer (continued). "Recent studies have found that TAMs highly express certain cytokines in gastric cancer, such as VEGF-A, VEGF-C, matrix metalloproteinase 1 (MMP-1) and amphiregulin, and induces capillary morphogenesis in human gastric cancer lymphatic ECs." (PMID 34988011, 2021). "Amphiregulin AREG and HB-EGF were provoking factors of intensified proliferation, migration, and functional CXCR4 expression in gastric cancer NUGC4 cells, with the overexpression of CXCR4." (PMID 29867026, 2018). "The expression of AREG, EGF, HB-EGF and TGFα in gastric tumours and body fluids of gastric cancer patients has been analysed in multiple studies." (PMID 27933395, 2017). "Both gastric ADAM17, and EGFR ligands HB-EGF, amphiregulin and EGF, are increased in patients with H. pylori infection and/or gastric cancer and are likely to contribute to epithelial hyperplasia." (PMID 25437333, 2013). "In this study, we analysed the involvement of the HER receptor ligands amphiregulin (AREG), epidermal growth factor (EGF), heparin-binding epidermal growth factor (HB-EGF) and transforming growth factor alpha (TGFα) in the responsiveness of gastric cancer cell lines to cetuximab and trastuzumab." (PMID 27933395, 2017). "For our analyses, we concentrated mainly on AREG, HB-EGF and TGFα, as previous results from our group had shown the absence of EGF secretion in gastric cancer cell lines." (PMID 27933395, 2017). "We concluded that IGF1R and AREG are prognostic, not predictive, markers of stage II/III gastric cancer." (PMID 26884344, 2017). "In our study, only HB-EGF, but not AREG or EGF, rescued sensitive gastric cancer cell lines from trastuzumab and cetuximab treatment." (PMID 27933395, 2017).
prostate carcinoma (16 papers, 2009 to 2025). A carcinoma that arises from epithelial cells of the prostate gland. "AREG is associated with several tumors, such as lung, breast, colorectal, ovary and prostate carcinomas, due to its role in tumorigenesis." (PMID 33712015, 2021). "Again, studies in other tumor entities revealed an ambiguous picture, with the HDAC1-, HDAC3- and HDAC6-specific inhibitor SN30028 leading to a persistent downregulation of amphiregulin in the prostate carcinoma cell line PC3." (PMID 39864337, 2025). "As an ectodomain of transmembrane glycoprotein of precursor, AREG is over-expressed in the epithelial tissue of gastric, pancreatic, colon, and prostate cancer, as well as renal cell carcinoma." (PMID 27713123, 2016). "AREG-targeted mAbs in preclinical development have shown promising anti-cancer effects in a variety of AREG-expressing cancer types, including ovarian, breast, and prostate cancer." (PMID 40727266, 2024). "Furthermore, AREG expression by a human prostate fibroblast cell line was sufficient to promote PD-L1 expression on PC3 prostate cancer cells." (PMID 34692707, 2021). "Given the critical role of Ras mutation-induced EGFR signaling activation in prostate cancer progression, we hypothesized that EGF-induced autocrine AREG, EREG, and TGFA expression might be directly mediated by miR-203 in RasB1 cells." (PMID 25004126, 2014). "More recently, it was shown that NTSR1 activation results in EGFR transactivation by the shedding of transforming growth factor-α (TGF-α) in pancreas, and HB-EGF or amphiregulin in prostate cancer cells, both leading to ERK1/2 activation, but also EGFR expression." (PMID 19156213, 2009). "The oncogenic potential of AREG and its role in tissue invasion & metastasis, angiogenesis, resistance to apoptosis etc., has been reported in human epithelial malignancies, such as lung, breast, colorectal, ovary and prostate carcinomas, as well as, in some haematological and mesenchymal cancers." (PMID 30517191, 2018). "The relationship between amphiregulin and EMT was here first reported in prostate cancer and as this protein can be secreted, will be further considered as a possible blood maker for monitoring metastatic occurrence." (PMID 39199549, 2024). "In human prostate cancer samples, expression of SASP factor amphiregulin (AREG) by senescent stroma was correlated with increased tumor expression of PD-L1." (PMID 34692707, 2021). "The pro-oncogenic activities of AREG and EREG have been examined in previous studies of lung, breast, colorectal, and prostate carcinoma." (PMID 32674321, 2020). "Moreover, we observed a high expression of AREG, EREG, and TGFA in tumors that had higher KRAS oncogenic response gene signatures in the human prostate cancer dataset." (PMID 25004126, 2014). "A prostate cancer related module was investigated (due to its significant enrichment on KEGG prostate cancer pathway), which has DEGs as PDGFRB, PDGFB, SNX2, EGFR and DECGs as (PDGFRA, PDGFRB), (SNX4, PDGFRB), (PDGFB, PDGFRA), (SNX2, PDGFRA), (PDGFRB, PIK3R2), (EGFR, PIK3R2), (EGFR, AREG)." (PMID 26070628, 2015).
psoriasis (15 papers, 2005 to 2024). An autoimmune condition characterized by red, well-delineated plaques with silvery scales that are usually on the extensor surfaces and scalp. "AREG encodes amphiregulin; over-expression in mice causes a psoriasis-like skin phenotype." (PMID 34769520, 2021). "Amphiregulin (AREG), a transcriptional target of YAP, was found to be upregulated in psoriasis, and overexpression of AREG promoted keratinocyte proliferation." (PMID 30323299, 2018). "AREG expression is upregulated in psoriasis, and overexpression of AREG promotes keratinocyte proliferation." (PMID 30323299, 2018). "In conclusion, the findings from our study suggest that YAP plays an important role through AREG in the abnormal proliferation and differentiation of keratinocytes in psoriasis." (PMID 30323299, 2018). "In some abnormal epidermal proliferative skin diseases such as psoriasis, AK, warts, keratoacanthoma and cSCC, the expression of AREG is also increased." (PMID 30323299, 2018). "EGF receptor (EGFR) ligands, including heparin-binding EGF-like growth factor (HB-EGF), amphiregulin and transforming growth factor (TGF)-α are also TACE substrates and are psoriasis-associated growth factors." (PMID 25384035, 2014). "Multiple EGFR ligands (TGF-α, amphiregulin, heparin-binding EGF-like growth factor) are overexpressed in psoriasis lesions, and transgenic expression of the human amphiregulin gene induces a psoriasis-like phenotype." (PMID 19551138, 2009). "In line with this hypothesis, Chung and colleagues reported that total E-cadherin levels are dramatically reduced in psoriatic lesions in a murine skin model treated with amphiregulin, a keratinocyte growth factor overexpressed in psoriasis." (PMID 36139479, 2022). "In the mouse samples, AREG could be found in 66.667% (4/6) of the samples from the IMQ-induced psoriasis group and in 16.667% (1/6) of the control samples." (PMID 30323299, 2018). "Given the linkage between amphiregulin and psoriasis, it is tempting to speculate that dysregulation of amphiregulin expression could promote a hyperactive wounding response." (PMID 29302364, 2017). "Transgenic mice expressing Amphiregulin under the control of keratin 14 promoter display early-onset synovial inflammation and severe skin pathology demonstrating a potential role for Amphiregulin in psoriasis and psoriatic arthritis." (PMID 16309552, 2005). "In this mouse model, TNF-α, amphiregulin, HB-EGF and TGF-α were significantly up-regulated in the skin lesions, similar to human psoriasis." (PMID 25384035, 2014). "We concluded that YAP may play an important role in the regulation of abnormal keratinocyte proliferation via an AREG-dependent pathway and that YAP could be a new target in the treatment of psoriasis." (PMID 30323299, 2018). "The significant induction of TNF-α increased IL-6, IL-8, EGF, HGF, TGF-α, epiregulin, and amphiregulin, but the increase in these cytokines and growth factors were not different among normal skin, uninvolved, and involved psoriasis." (PMID 20161853, 2009).
hepatocellular carcinoma (14 papers, 2012 to 2026). A malignant tumor that arises from hepatocytes. "Amphiregulin (AREG), an epidermal growth factor receptor ligand, is associated with human liver cirrhosis and hepatocellular carcinoma." (PMID 37868614, 2023). "Functionally, AREG counteracts NK cell‐mediated tumor apoptosis, while the adoptive transfer of AREG‐deficient human NK cells significantly suppressed melanoma, cutaneous squamous cell carcinoma (cSCC), and hepatocellular carcinoma growth in NCG mice." (PMID 41082397, 2026). "Consistently, AREG levels in serum from hepatocellular carcinoma patients were higher than those in serum from a healthy population." (PMID 36639835, 2023). "AREG is expressed in human hepatocellular carcinoma tissues and cell lines and behaves as a mitogenic and antiapoptotic growth factor for hepatocarcinoma cells." (PMID 24860833, 2014). "Mitochondrial dysfunction-increased ROS might upregulate amphiregulin to promote cell migration of hepatoma cells." (PMID 37525297, 2023). "In addition, mitochondrial dysfunction-increased ROS upregulates amphiregulin to promote chemoresistance in hepatoma cells." (PMID 37525297, 2023). "Calcium was also found to be involved in mitochondrial dysfunction-mediated amphiregulin upregulation, which contributes to chemoresistance and cell migration of hepatoma cells, and drug resistance to endocrine therapy in hormone receptor-positive breast cancer cells." (PMID 37525297, 2023). "In cervical cancer and hepatocellular carcinoma, YAP1 can activate EGFR signaling by upregulating the expression of TGF-α or AREG." (PMID 29228705, 2017).
melanoma (13 papers, 2015 to 2026). A malignant, usually aggressive tumor composed of atypical, neoplastic melanocytes. "Resistance to MEK inhibitors has been associated with HGF in melanoma while resistance to PI3K inhibitors has been associated with AREG, among other factors." (PMID 40411295, 2025). "To determine if CD133 also upregulates AREG expression in other melanoma cell lines, we established another Dox-inducible cell line derived from a second patient-derived melanoma (POT), harboring an NRASQ61R mutation." (PMID 38727313, 2024). "The NK cells were incubated with target cells for 6 h, showing that WT and AREG KO NK cells induced comparable specific lysis of melanoma (A375, A2058) and liver cancer (Huh7) cell lines." (PMID 41082397, 2026). "Potential mechanisms highlighting the role(s) of CD133 and AREG in melanoma CSC were further delineated using AREG/EGFR inhibitors or siRNA knockdown of AREG mRNA." (PMID 38727313, 2024). "Dox induction increased CD133 expression ~16-fold, resulting in an ~8-fold upregulation of AREG in BAKP melanoma cells." (PMID 38727313, 2024). "Further, this induction of AREG by CD133 was shown in two independent melanoma cell lines, as was its role in the increased MAPK pathway activation and proliferation." (PMID 38727313, 2024). "In any case, these findings point to AREG as a potential therapeutic target in CD133/EGFR-driven melanoma stem cells." (PMID 38727313, 2024). "While the importance of an AREG/EGFR loop in melanoma is less studied, a role for AREG expression in melanomagenesis has been demonstrated." (PMID 38727313, 2024). "These melanoma-infiltrating NK cells also exhibited high AREG expression, an epidermal growth factor (EGF) receptor ligand." (PMID 38956379, 2024). "Since AREG precursor protein is released extracellularly as soluble AREG ligand after cleavage by metalloprotease TACE/ADAM17, we next determined if AREG TM precursor is likewise secreted as AREG ligand by BAKP melanoma cells." (PMID 38727313, 2024). "Our results, taken together with the previous reports, suggest that the expression of IL13Rα2 enhances melanoma tumorigenesis in vivo via promoting angiogenesis through the expression of angiogenesis-triggering factors such as amphiregulin." (PMID 30718742, 2019). "We further investigated the effects of induced CD133 expression and consequent AREG upregulation on cell proliferation and cell growth in patient-derived human melanoma cells and tested the feasibility of targeting AREG by siRNA and eventually small molecule or antibody-based inhibitors." (PMID 38727313, 2024). "The cross-suppression of both AREG and EREG has also been reported to lead to the emergence of CTX resistance, which is related to the loss of cell addiction to EGFR, compensated by the hyperactivation and addiction to FGFR3 in melanoma." (PMID 36899869, 2023). "If AREG has also an influence on melanoma cells will be the topic of a further study." (PMID 33562468, 2021). "To study whether amphiregulin-dependent tumour growth was mediated by enhanced angiogenesis, we investigated whether altered amphiregulin expression would affect new vessel formation in melanoma tumour tissues." (PMID 30718742, 2019). "In accordance with the present in vitro and in vivo analyses in various melanoma cells, TCGA analysis showed that IL13RA2 expression was correlated with AREG expression in malignant melanoma patients, suggesting that IL13Rα2 regulated amphiregulin expression in human melanoma patients." (PMID 30718742, 2019). "However, detailed mechanisms how IL13Rα2 regulates the expression of amphiregulin and proliferation of melanoma cells need to be elucidated in the future." (PMID 30718742, 2019). "We observed that PECAM-1-positive vascular area in the tumours derived from the SK-amphiregulin cells was significantly larger than that in the tumours derived from SK-GFP cells, implying that amphiregulin expression in malignant melanoma enhanced angiogenesis." (PMID 30718742, 2019).